INS (insulin)
Diseases named in the same sentence as INS in open-access papers (continued):
Sharing a sentence is not in itself a finding about the gene and the disease.
diabetes (continued). "The long-awaited automated insulin delivery systems represent the latest devices in engineering excellence however it is important that we do not lose sight of the fact that there is a person at the end of this technology, simply wanting a better life with diabetes with reduced diabetes burden." (PMID 29632586, 2016). "Despite the fact that both compounds could significantly recover the antioxidant capacity in serum and the liver, however the diabetes-induced complications including blood glucose and insulin levels were remained high and low respectively in the MEL-treated diabetic rats." (PMID 27980584, 2016). "Diabetes mellitus (DM) is a metabolic disorder characterized by the destruction of pancreatic β cells or diminished insulin secretion and action insulin." (PMID 27092490, 2016). "Diabetes mellitus (DM) is a metabolic disorder of multiple etiologies characterized by elevated levels of blood glucose resulting from defects in insulin production, insulin action, or both." (PMID 26739611, 2016). "However, the elevated levels of AST, ALT and ALP in the diabetic rats treated with insulin during the period of the experiment could be as a result of damage to the liver and the heart from poorly controlled diabetes mellitus." (PMID 27846886, 2016). "Diabetes mellitus (DM) is a group of metabolic diseases resulting from impaired insulin secretion and/or action." (PMID 27893660, 2016). "Diabetes mellitus (DM) is a group of metabolic diseases which are characterized by hyperglycemia, resulting from defects in insulin secretion, insulin action, or both." (PMID 27635130, 2016). "However, the present study clearly indicated that the increased insulin release from pancreatic beta cells might be responsible for improvement of diabetes after garlic and resveratrol treatment." (PMID 27790139, 2016). "Additionally, diabetes may develop as a result of insulin resistance, a condition in which the body cannot effectively use the insulin produced by β-cells." (PMID 27881904, 2016). "For instance, overexpression of SIRT1 reduces diabetes-exacerbated myocardial ischemia-reperfusion injury and oxidative stress via activating eNOS in diabetic rats, and the vasculoprotective effect of insulin after arterial injury is mediated by an eNOS-dependent mechanism." (PMID 26879172, 2016). "In mammals, the Tubby gene (Tub) belongs to a family of genes of unknown function and mutation of this gene has been found to cause obesity in rodents, with persistent elevation of insulin, but without development of diabetes." (PMID 27053133, 2016). "Interestingly, the patients with desired glycaemic control showed a more negative impact of diabetes on QoL than those with less than optimum control; this association was moderated by treatment modality (use of insulin)." (PMID 27695086, 2016). "Taken together, these results suggest that regular consumption of pistachios, as part of a moderate-fat diet, could have important glucose- and insulin-lowering effects, promote a healthier metabolic profile, and reverse certain metabolic consequences of pre-diabetes." (PMID 26944400, 2016). "Hence, it is important to control the dosage of insulin in diabetes patients." (PMID 27212152, 2016). "In addition to patients with type 1 diabetes mellitus, those with type 2 diabetes might also eventually require insulin therapy." (PMID 27725943, 2016). "In case of near-total insulin deficiency, transient glucagon receptor blockade could also serve as a means to increase the α-cell mass before triggering insulin production in these cells, a strategy that might be envisioned as a novel therapy to treat diabetes." (PMID 27092792, 2016). "Diabetes mellitus (DM) is a group of metabolic disorders characterized by circulating hyperglycemia resulting from either defect in insulin secretion or insulin action." (PMID 27190643, 2016).
diabetes (continued). "Since, in a postprandial state, not only higher plasma glucose level but also incretin effects stimulate insulin secretion, postprandial C-peptide level more likely reflects the maximal insulin secretory capacity compared with fasting C-peptide level, especially in patients with diabetes." (PMID 27196896, 2016). "Furthermore, the insulin-free period (13.6 ± 6.4 vs. 4.3 ± 5.7 years, P<0.0001) and the duration before the diagnosis of GADAb-positive diabetes (9.4 ± 7.4 vs. 6.7 ± 8.9 years, P<0.001) were significantly longer in the NIR-SPIDDM patients than in the IR-SPIDDM patients." (PMID 27177031, 2016). "Although it is acknowledged that elevated MnSOD could protect against diabetes by down-regulating ROS in β cells and enhancing insulin secretion, some debate remains regarding whether increased MnSOD expression has beneficial or deleterious effects on muscle insulin sensitivity." (PMID 27258818, 2016). "Although we did not observe an association between DNA methylation at cg26963277 and expression of KCNQ1, our results provide evidence that smoking may increase the risk of diabetes through decreased methylation at KCNQ1 and a subsequent decrease in fasting insulin levels." (PMID 26825526, 2016). "Altogether, this information demonstrates that there is a positive feedback mechanism between insulin secretion, insulin signaling, L-arginine/NO pathway, and cardiac function that is disrupted in pathophysiological conditions such as metabolic syndrome, insulin resistance and diabetes." (PMID 27014078, 2016). "There is an argument that increasing insulin dose could be a measure of diabetes deterioration." (PMID 27152598, 2016). "Increased SMBG as a result of the intervention may not only help adolescents more effectively manage their daily blood glucose levels, but provide endocrinologists and diabetes educators with sufficient data to assist families in making appropriate changes, if needed, to their insulin dosing." (PMID 27610391, 2016). "Although UCPCR can be used at any stage in diabetes to confirm endogenous insulin levels, in the current study ≥5 years’ duration was chosen to avoid misclassifying people with early type 1 who may have been still producing their own insulin." (PMID 27080317, 2016). "Furthermore, reduction of diabetes has been found to occur more frequently among patients who underwent gastric bypass surgery that excluded the duodenum from the nutrient pathway and changed the bowel metabolism, thus reducing insulin resistance faster." (PMID 27812597, 2016). "Diabetes mellitus (DM) is characterized by chronic hyperglycaemia which results from defects in insulin secretion (type 1 DM), insulin action (T2DM), or both." (PMID 27014078, 2016). "Emerging data from physiological and genetic studies indicate that islet dysfunction and loss of beta-cell mass are the key determinants of whether an insulin-resistant state will progress to frank hyperglycemia/hyperlipidemia and diabetes; insulin resistance alone is insufficient to predict T2DM." (PMID 26959059, 2016). "Additionally, low muscle mass adversely affects insulin resistance and may be a predictor of diabetes incidence." (PMID 27832095, 2016). "In our study, several individuals with diabetes were normal or underweight, which may suggest that insulin-dependent or Type I diabetes is also an important health burden in the region, and further epidemiology work is needed to understand this potentially important distinction." (PMID 27711179, 2016). "High fasting blood glucose (FBG) level is considered as a hallmark feature of diabetes mellitus, owing to a loss or lack of insulin-producing pancreatic β-cells (type Ι diabetes) or via loss of insulin sensitivity in its target tissues like muscle and adipose (type II diabetes)." (PMID 27602318, 2016). "Therefore identifying new molecular mechanisms contributing to insulin secretion could improve the understanding, treatment and prevention of diabetes." (PMID 27841257, 2016).
diabetes (continued). "The proposed scenarios between diabetes and dementia are numerous; they include vascular lesions, inflammation, oxidative stress, elevated end products of glycolysis, insulin resistance, abnormal insulin receptor signaling, and degradation of insulin and its relation to Aβ protein deposits." (PMID 27547756, 2016). "In addition, other factors could contribute to the decrease in DKA, for example, changing the modality of treatment or the insulin regime, increased general improvement of care, and the increase in general awareness of diabetes." (PMID 27294150, 2016). "Diabetes mellitus (DM) is a metabolic disorder characterized by dysfunction of insulin-secreting pancreatic beta-cells with great importance for the development of CAD." (PMID 26558258, 2015). "The relative risk for the glucose tolerance impairment (diabetes and pre-diabetes) was 2.78 (95% CI: 1.31-5.88, P = 0.07).Six and a half percent of the Alpha-thalassemia group and 2.5% in the control group had 2.25 ≤ HOMAIR ≤ 3.59 (an intermediate state of Insulin sensitivity) p = 0.443." (PMID 25722965, 2015). "This increased risk of death seems to be due mainly to insulin-treated diabetes; the mortality estimates for nondiabetic patients and noninsulin-treated diabetic patients were similar, with the mortality estimate for insulin-treated patients substantially worse." (PMID 25880202, 2015). "Therefore, optional selection between insulin treatment and proper glucose control may be needed for patients with diabetes, particularly T2DM." (PMID 25866823, 2015). "Besides, some studies also reported that vitamin D treatments could reduce insulin levels and ameliorate insulin resistance in experimental diabetes models." (PMID 25774877, 2015). "In addition to the physiological influence that stress has on glycemia, stress interferes with the ability to self-manage diabetes such as monitoring glucose frequently, following a meal plan and correctly preparing or remembering to take insulin or oral medication at the right time." (PMID 25928592, 2015). "This subgroup had the highest age, the longest diabetes duration and the highest proportion with HbA1c > 7% (53 mmol/mol) and hypertension (RR>140/80 mmHg) despite the highest proportion receiving antihypertensive medication (65.9%, compared with 49.1% of the entire group) and insulin." (PMID 26177037, 2015). "However, the total number of basal insulin units in patients with type 1 and type 2 diabetes mellitus decreased significantly from 14.4 ± 5.1 unit and 13.4 ± 7.6 unit at baseline to 12.3 ± 5.0 unit and 11.9 ± 6.7 unit at 12 weeks, and to 12.3 ± 6.1 unit and 11.4 ± 6.3 unit at 24 weeks, respectively." (PMID 26819737, 2015). "Moreover, systemic or hepatic blockage of RANKL signaling in genetic and nutritional mouse models of type 2 diabetes mellitus resulted in a marked improvement of hepatic insulin sensitivity and amelioration or even normalization of plasma glucose concentrations and glucose tolerance." (PMID 25873952, 2015). "A compensatory increase in insulin secretion due to insulin resistance is observed in the impaired-glucose-tolerance stage and in the very early stage of Type 2 diabetes mellitus (DM)." (PMID 26097511, 2015). "It has been recently shown that zinc supplementation appears to differently affect the early insulin response to glucose, according to rs13266634 genotype, and could be beneficial for diabetes prevention and/or treatment for some individuals based on SLC30A8 variation." (PMID 26559814, 2015). "Diabetes mellitus (DM) is a group of chronic metabolic disorders characterised by inappropriate levels and/or utilisation of the hormone insulin, leading to elevated blood glucose concentrations." (PMID 26556589, 2015).
diabetes (continued). "There was a positive correlation between the duration of diabetes and the duration of insulin therapy (Pearson’s correlation coefficient = 0.40), as well as between the frequency of insulin administration and the daily insulin dose (Pearson’s correlation coefficient = 0.51)." (PMID 26124906, 2015). "Diabetes mellitus (DM) is a metabolic consequence of a decrease in insulin production and/or activity characterized by hyperglycemia and vascular and nerve impairment." (PMID 26075282, 2015). "On the other hand, patients with type 1 diabetes mellitus are well aware that insulin therapy is essential for life support, and basal insulin is often administered simultaneously with bolus insulin, so these patients may not feel the benefits of flexible injection of degludec." (PMID 26819737, 2015). "Type 2 diabetes mellitus (DM) is characterized by impaired insulin secretion, and increased insulin resistance (or resistance to insulin mediated glucose disposal)." (PMID 26705405, 2015). "Finally, several studies suggest that vitamin D could play a role in the pathogenesis of diabetes mellitus type 2 by affecting insulin sensitivity of β cell function." (PMID 26000285, 2015). "Therefore, a dysfunction of the beta cell in diabetes can disrupt insulin secretion, reduce the level of insulin in the brain and may affect this mechanism thus leading to glucose dysregulation." (PMID 26193295, 2015). "The rapidly increasing diabetes mellitus (DM) is becoming a major public health issue globally; considerable progress has been made in the field of western hypoglycemic drug and insulin, but some shortages still exist." (PMID 26508987, 2015). "Type 2 diabetes mellitus (T2DM) formerly known as non-insulin dependent diabetes mellitus (NIDDM) or adult-onset diabetes is the most markedly growing chronic disease mainly caused by impairment in insulin secretion and insulin action." (PMID 25888350, 2015). "When there are defects of insulinsecretion, insulin actions, or both, the result is diabetes mellitus (DM)." (PMID 26176316, 2015). "Therefore, it is interesting to investigate whether Cdr1as, as a powerful miR-7 inhibitor/sponge, could improve the adaptation of islet cells for insulin secretion and could ultimately serve as a potential treatment target for obese diabetes." (PMID 26211738, 2015). "This strategy may facilitate effective insulin therapy in routine medical practice, compensating for any reluctance on the part of physicians to optimize insulin therapy and thus to improve the achievement of recommended targets of diabetes care." (PMID 25904987, 2015). "While insulin-target organs are resistant to the actions of insulin in diabetes, hyperinsulinemia may have progrowth effects on a nascent tumour by allowing the tumour to overcome an important early barrier in tumourigenesis, that is, lack of growth factor signaling." (PMID 25961014, 2015). "However, diabetes mellitus impairs the normal function of islets to secrete sufficient insulin." (PMID 26176625, 2015). "Drivers with non-insulin treated diabetes have received less scrutiny despite the fact that the risk of severe hypoglycemia with sulfonylurea therapy is similar to that of people with T2DM who have been treated with insulin for less than two years." (PMID 28702227, 2015). "When multivariable models were adjusted for the Matsuda index, fasting glucose and fasting insulin, results were similar in all cases to those seen with adjustment for HOMA2-IR, though the latter metric had the most consistent impact on the associations between adiposity and diabetes." (PMID 25645144, 2015). "Both apoptosis of β-cells and their decreased sensitivity towards insulin can lead to diabetes and result in hyperglycaemia, while an increased function caused by either insulin-producing tumours (e.g. insulinoma) or by hyperplastic β-cells (e.g. nesidioblastosis) may lead to hypoglycaemia." (PMID 25855967, 2015).
diabetes (continued). "However, the contribution of metabolic alterations in diabetes such as reduced insulin levels and/or impaired insulin signalling to the deranged UPR, thereby propagating a maladaptive ER response, particularly in podocytes remains unknown." (PMID 25754093, 2015). "Furthermore, CHMs have been used to successfully treat diabetes via increased insulin secretion and sensitivity, enhanced glucose uptake by adipose and muscle tissues, inhibition of glucose absorption by the intestine, inhibition of glucose production by hepatocytes, and anti-inflammatory activity." (PMID 26699542, 2015). "Attendance at an insulin pump assessment is required for initiation of insulin pump therapy through this diabetes clinic and at the time of this study, families were waiting 12–18 months for pump assessments, during which, many may have solidified their intention to start pump therapy." (PMID 25889602, 2015). "Diabetes mellitus (DM) is a metabolic disorder characterized by chronic hyperglycemia, resulting from defects on either insulin secretion or action." (PMID 26244369, 2015). "Hence, there is a considerable interest in seeking complementary and alternative approaches in improving implant success in diabetes, especially orally available drugs which could mimic insulin action and somehow overcome insulin resistance." (PMID 26783411, 2015). "According to the results of our unadjusted analysis, amputation was directly associated with age, sex, the number of years of insulin therapy, the lack of suitable shoes, higher BMI values, smoking, a history of diabetes among close family members, and irregular HbA1c monitoring." (PMID 26493777, 2015). "Therefore, statin therapy for patients with diabetes may improve insulin secretion by increasing vitamin D synthesis, which in turn can improve the diabetic state resulting in a reduced risk of TB." (PMID 25993300, 2015). "Transgenic mice overexpressing miR-7 in β cells developed diabetes due to reduced insulin secretion and impaired β cell dedifferentiation, whereas that inactivation of miR-7 in obese mice might be sufficient to rescue β cell failure and glycemia by enhancing β cell maturity and pancreatic function." (PMID 26211738, 2015). "Our study showed that insulin could not counterbalance all the negative changes caused by diabetes, which was in agreement with former studies showing that the BIC and removal torque were significantly lower compared to the healthy controls." (PMID 26783411, 2015). "Furthermore, this obesity-driven combination of low insulin sensitivity with an inability of pancreatic beta cells to increase insulin secretion sufficiently to maintain glucose homeostasis, leads to hyperglycaemia and eventually to diabetes." (PMID 26405763, 2015). "However, family and other instrumental support systems are by far not enough; other sources of stress should be resolved through improving treatment and care, by increasing access to insulin, glucometers, strips and other basic medical essentials for patients with diabetes." (PMID 25928592, 2015). "Consideration of the reciprocal interaction between lung function and diabetes mellitus in clinical practice has been indicated to potentially improve outcomes as well as to reduce the healthcare burden of both respiratory and diabetic diseases as well as insulin-resistant states." (PMID 26542243, 2015). "Our findings suggest that isotopic breath CO2 is a novel method for accurate estimation of ISI0,120 and thus may open new perspectives into the isotope-specific non-invasive evaluation of insulin resistance for large-scale real-time diabetes screening purposes." (PMID 26148706, 2015). "Additionally the association of these conditions with age, gender, nutritional intake, concurrent alcohol intake, risk factors for viral hepatitis, BMI, waist-to-hip ratio, serum glucose, insulin, and diabetes mellitus, serum cholesterol and triglycerides are investigated." (PMID 26386597, 2015).